APOE (apolipoprotein E)
Diseases named in the same sentence as APOE in open-access papers (continued):
Sharing a sentence is not in itself a finding about the gene and the disease.
Hypercholesterolemia (continued). "In addition, ApoE-deficient mice have been shown to develop severe hypercholesterolemia most likely caused by the delayed clearance of large atherogenic particles from the circulation." (PMID 31404961, 2019). "Key findings of the present study are that diet-induced hypercholesterolemia in APOE*3-Leiden mice caused a pre-ischemic peripheral monocytosis, in particular of the Ly-6Chi pro-inflammatory monocytes, and impaired intrinsic LV function eight weeks after acute MI-R." (PMID 31199833, 2019). "Thus, apolipoprotein E deficiency (ApoE−/−) mice are wildly used in order to mimic and better understand this hypercholesterolemia-associated process." (PMID 31249639, 2019). "However, hypercholesterolemia in apoE−/− mouse is often associated with systemic inflammation including in skin." (PMID 30972070, 2019). "In this study, we evaluated the influence of aging and hypercholesterolemia on serum pro-inflammatory cytokines, oxidative stress, DNA damage and apoptosis in monocytes from apolipoprotein E-deficient (apoE−/−) mice compared with age-matched wild-type C57BL/6 (WT) mice." (PMID 30185234, 2018). "This profile mirrored the immuno-inflammatory response associated to hypercholesterolemia and confirmed that allogenic skin graft rejection was independent of the systemic metabolic environment, suggesting a mechanism dependent on leukocyte-produced apoE." (PMID 30082772, 2018). "Knockout of APOE causes hypercholesterolemia, which in turn leads to chronic kidney disease." (PMID 28986523, 2017). "Furthermore, hypercholesterolaemia associated with ApoE deficiency was shown to lead to renal injury." (PMID 27538678, 2016). "ApoE deficiency is a commonly used laboratory model of hypercholesterolemia." (PMID 25502628, 2014). "Our results strongly suggest that γδT cells infiltrate aortic adventitia in healthy mice, but in the setting of ApoE deficiency and its associated hypercholesterolemia they are recruited to the aortic intima, where they can become activated and/or promote local inflammation." (PMID 25313857, 2014). "Among the available models, the apolipoprotein E-deficient (apoE-/-) mouse is of particular relevance because of its propensity to spontaneously develop hypercholesterolemia and atherosclerotic lesions that are similar to those found in humans, even when the mice are fed a chow diet." (PMID 22082357, 2011). "Moreover genome-wide association studies (GWAS) have also shown an association of the APOE locus with hypercholesterolemia but they were unsuccessful in establishing its relationship with statin response when whole-genome platforms were used." (PMID 22074026, 2011). "The murine model that lacks the functional gene encoding the apolipoprotein E (ApoE), which spontaneously develops hypercholesterolemia and atherosclerotic lesions similar to those found in human beings has greatly contributed to the understanding of these disorders." (PMID 22117541, 2011). "In this sense, the present model of uremic apoE-/- mice has the advantage of sharing the same etiology with human AS in patients whose aortic valve disease is associated with chronic renal failure and hypercholesterolemia." (PMID 19257900, 2009). "However, the SKH-hr2+ApoE mice demonstrated a greater increase in the sebum levels, which may be associated with their hypercholesterolemia, as previously suggested." (PMID 39456640, 2024). "However, ApoE-/- mouse causes severe hypercholesterolemia and spontaneous AS." (PMID 36311729, 2022). "Subsequently, we examined whether the pathological exacerbation of ApoE deficiency is due to direct hypercholesterolemia or indirectly mediated by loss of the ApoE gene, since APOE has been reported to possess several pleiotropic effects that influence cell signaling." (PMID 33895138, 2021). "Additionally, it is well-known that apoE-deficient mice have hypercholesterolemia." (PMID 33072621, 2020).
Hypercholesterolemia (continued). "Lactobacillus mucosae DPC 6426 has been shown to attenuate the dyslipidaemia and hypercholesterolemia observed in apolipoprotein-E deficient mice maintained on a high-fat/cholesterol diet, and may have application as a potential therapy or adjunct to pharmaceutical CVD intervention." (PMID 30736731, 2019). "Therefore, the apolipoprotein E-deficient (apoE-/-) mouse is considered to be the most relevant model because the animals develop spontaneous hypercholesterolemia and consequently endothelial dysfunction accompanied by arterial lesions that are similar to those observed in humans." (PMID 22849299, 2012). "Our achievement can be explained by the concurrence of hypercholesterolemia, endothelial dysfunction, age (20 weeks old) and gender, i.e., female apoE-/- mice may be more susceptible to develop endothelial dysfunction, and a female gender may facilitate the progression of vessel stenosis." (PMID 22849299, 2012). "Given the role of cholesterol in facilitating viral entry and modulating immune responses 47, we employed ApoE-/- mice, a model of hypercholesterolemia 47, to investigate how cholesterol imbalance affects mRNA vaccine-induced responses at the injection site." (PMID 40963900, 2025). "As expected, plasma total cholesterol and triglyceride levels were markedly elevated in ApoE-/- mice, confirming the successful induction of hypercholesterolemia." (PMID 40963900, 2025). "To assess the efficacy of mRNA vaccination within the context of hypercholesterolemia, we evaluated variations in immune responses across different diets and their interactions with ApoE gene status." (PMID 40963900, 2025). "Because female apoE KO rabbits had similar high hypercholesterolemia to WT rabbits, our results indicate that apoB48-rich remnant lipoproteins indeed are more atherogenic." (PMID 39087075, 2024). "Male apoE KO rabbits exhibited more pronounced hypercholesterolemia and hypertriglyceridemia compared to their WT counterparts when fed a CRD." (PMID 39087075, 2024). "The same was true even in patients with a family history of hypercholesterolemia, indicating that LDL receptor function has a more direct effect on CHD risk than APOE." (PMID 39766777, 2024). "Cholesterol-induced suppression of Kir currents was also observed in endothelial cells freshly-isolated from hypercholestreolemic animal models, diet-induced hypercholesterolemia in pigs and genetically-induced hypercholesterolemia in ApoE−/− mice." (PMID 38333595, 2024). "ApoE KO mice showed hyperlipidemia even on a chow diet and exhibited severe hypercholesterolemia (>2,000 mg/dl) when on a Western-type diet while plasma triglycerides (TG) were minimally increased." (PMID 39087075, 2024). "Since prescription of statins typically occurs for individuals with hypercholesterolemia, we utilized FCG mice on a C57BL/6 background that develop hypercholesterolemia on a chow diet due to genetic ablation of the apolipoprotein E (apoE) gene." (PMID 38956041, 2024). "We found two variants in APOE, a gene that is associated with coronary artery disease in OMIM, and a variant in PCSK9, a gene that is linked to familial hypercholesterolemia." (PMID 39460944, 2024).
Hypercholesterolemia (continued). "The pro-oxidant enzymes NOX and XDH/XO were previously shown to contribute to vascular damage during hypercholesterolemia in ApoE−/− mice." (PMID 37873768, 2023). "Our results demonstrated that dietary supplementation with DADS can significantly alleviate hypercholesterolemia and hyperleptinemia, which is accompanied by a decrease in adipose tissue weight in WD-fed ApoE−/− mice." (PMID 37138269, 2023). "ApoE‐KO aorta showed the breakdown of acetylcholine‐induced vasodilation, suggesting the endothelial damage by hypercholesterolemia." (PMID 36068079, 2023). "All of these differences in gene expression were more remarkable in pre-eclampsia-like mouse models with worse lipid profiles, such as EOPE, a high-fat diet group, and ApoE-knockout mice (suffering hypercholesterolemia)." (PMID 37764661, 2023). "In animal studies, ApoE-/- mice are often used to simulate the pathological symptoms of hypercholesterolemia." (PMID 38048213, 2023). "Those with the APOE e4 gene have an increased odds of MRI markers of cerebrovascular disease and clinical outcomes of hypercholesterolaemia and ischaemic heart disease." (PMID 37261323, 2023). "We also conducted an additional gene co-localisation analysis, identifying four genes, namely CELSR2, PCSK9, LPA, and APOE, co-localised with hypercholesterolaemia and IHD." (PMID 38144368, 2023). "ApoE-knockout (ApoE-KO) mice have been commonly used in research of AS, due to their development of AS features such as hypercholesterolemia in response to a high-fat diet (HFD)." (PMID 37215106, 2023). "Our results demonstrate that dietary supplementation with capsaicin can significantly alleviate hypercholesterolemia as well as hyperleptinemia, which is accompanied with a marked decrease in adipose tissue weight in WD-fed ApoE-/- mice." (PMID 38084147, 2023). "In our research, ApoE-/- mice were utilized to mimic the symptoms of hypercholesterolemia, and high plasma cholesterol levels were observed in the ApoE-/- mice, in line with Tsukahara’s research." (PMID 38048213, 2023). "ApoE−/− rats exhibited hypercholesterolemia, as evidenced by plasma cholesterol levels that were up to tenfold higher, and total hepatic cholesterol levels that were up to threefold higher than the control rats at the end of the study." (PMID 38079017, 2023). "Together, our results indicate that the decrease in liver ER stress markers by capsaicin supplementation leads to a clear improvement of hypercholesterolemia in WD-fed ApoE-/- mice." (PMID 38084147, 2023). "Signally reduced mRNA levels of PSD-95 and BDNF were found in ApoE-/- mice, which were markedly increased by Atorvastatin, further verifying the protective property of Atorvastatin against the memory impairment in hypercholesterolemia mice." (PMID 38048213, 2023). "ApoE-/- mice were utilized to mimic the state of chronic hypercholesterolemia and were divided into four groups." (PMID 38048213, 2023). "Our data supports this, showing that the decrease in adipose tissue weight and hepatic ER stress markers by DADS supplementation resulted in a clear improvement of hyperleptinemia and hypercholesterolemia in WD-fed ApoE−/− mice." (PMID 37138269, 2023). "Apolipoprotein E (ApoE) knockout mice, which are characterized by hypercholesterolemia and hypertriglyceridemia, displayed an MGD phenotype, including MG dropout, abnormal MG acinar morphology, dilated MG duct and plugging of the MG orifice." (PMID 36983132, 2023). "ApoE−/− serum cholesterol was double that of SD rats (mean 2.25 vs. 1.10 mg/ml, p < 0.001) indicating a relatively mild hypercholesterolemia phenotype." (PMID 37046262, 2023). "We used an ApoE−/− rat model to mimic familial hypercholesterolemia and found these rats, when fed a regular chow diet, had double the total blood cholesterol of our SD rats at euthanasia." (PMID 37046262, 2023).
Hypercholesterolemia (continued). "ApoE–/– mice has been confirmed as an animal model to develop obvious hypercholesterolemia, with elevated LDL level and decreased HDL level." (PMID 35845572, 2022). "Through comprehensive analyses of collecting lymphatic function using vessels from hypercholesterolemic ApoE−/− mice, we demonstrate here that hypercholesterolemia significantly compromises the contractile, valve and barrier functions of collecting lymphatics." (PMID 36685213, 2022). "Additional evidence to support the important role of hypercholesterolemia in aneurysm formation is the increased AAA formation in angiotensin II (Ang II) infused ApoE−/− mice (hypercholesterolemia mouse model) compared with wild-type (WT) C57BL/6 mice." (PMID 35207478, 2022). "Firstly, we confirmed that ApoE−/− mice had a significant increase in body weight and weight gain in addition to hypercholesterolemia and hypertriglyceridemia, being significantly higher in ApoE−/− fed with HFD for 18 weeks." (PMID 36142173, 2022). "APOE KO mice exhibited severe hypercholesterolemia with average plasma total cholesterol concentrations of >1000 mg/dL after 6 weeks of Western-type diet feeding." (PMID 36139044, 2022). "ApoE is a potent suppressor of AS, while ApoE-knockout mice display elevated inflammatory responses to long term diet-induced hypercholesterolemia." (PMID 35967343, 2022). "Like the effect of adipose tissue expansion on collecting lymphatics, hypercholesterolemia in ApoE−/− mice reduced the contractile function of collecting vessels and compromised valve function." (PMID 36685213, 2022). "Although our analysis revealed that hypercholesterolemia significantly altered the barrier function of collecting lymphatics, hyperpermeability was only characteristic of half the ApoE−/− vessels." (PMID 36685213, 2022). "Although APOE KO mice are protected against diet-induced obesity, it spontaneously develops severe hypercholesterolemia and atherosclerotic lesions." (PMID 36036283, 2022). "A switch to a chow diet induced a reduction in the hypercholesterolemia extent and increased the absolute lesion size and plaque collagen-to-macrophage ratio in Western-type-diet-fed APOE KO mice." (PMID 36139044, 2022). "Here, we examined the effect of chronic hypercholesterolemia on inflammation and memory function in Apolipoprotein E (ApoE) knockout mice and normocholesterolemic wild-type mice." (PMID 34349106, 2021). "Studies of dyslipidemia using ApoE-/- mice demonstrate decreased clearance of remnant lipoproteins that leads to hypercholesterolemia and hypertriglyceridemia." (PMID 33626069, 2021). "ApoE-/- mice characterized by severe hypercholesterolemia due to a virtually completely blocked LDL-receptor mediated lipoprotein remnant clearance, fed with HFD, have been widely reported as a classical AS model." (PMID 34264978, 2021). "Therapeutic cholesterol-lowering through simvastatin reduced systemic and neuro-inflammation, and the occurrence of memory deficits in aged ApoE-/- mice with chronic hypercholesterolemia." (PMID 34349106, 2021). "Using an experimental hypercholesterolemia animal model such as ApoE-KO mice, the effects of chronic intake of AEPs or AETa were investigated." (PMID 34335290, 2021).
Hypercholesterolemia (continued). "Even though Dscr-1−/− alone did not affect the systemic cholesterol clearance, once ApoE-null mutation was combined with Dscr-1−/−, the mice developed steatohepatitis and a more severe hypercholesterolemia, than ApoE-null background alone." (PMID 33895138, 2021). "Our data indicated that Dscr-1 and ApoE double null mice experienced significant hypercholesterolemia, while atherosclerotic plaque levels in the aorta were reduced." (PMID 33895138, 2021). "Nonetheless, one study has investigated the effect of 4 week diet-induced hypercholesterolemia on left ventricle (LV) remodelling following IR in these mice in comparison to normocholesterolemic ApoE*3-Leiden mice." (PMID 33258000, 2020). "ApoE−/− mice demonstrate decreased cholesterol clearance of remnant lipoproteins, which results in hypercholesterolemia." (PMID 32967121, 2020). "The sustained enhanced activation of T cells was accompanied by the expansion of lymph nodes in atherosclerotic ApoE - / - mice, as well as the local and systemic pro-inflammatory response, to further enhance the diet induced by hypercholesterolemia." (PMID 33052139, 2020). "We previously reported that hypercholesterolemia induces tendinopathy in Achilles tendons of ApoE −/− mice." (PMID 32197645, 2020). "To simulate hypercholesterolemia in vivo, we used ApoE −/− mice (10 months old, male) as the hypercholesterolemic group, while C57BL/6 mice (10 months old, male) were the control group." (PMID 32197645, 2020). "ApoE knockout mice (ApoE−/−) mice display delayed lipoprotein clearance and develop dyslipoproteinemia, hypercholesterolemia and atherosclerotic lesions even when fed normal chow." (PMID 33258000, 2020). "Hypercholesterolemia aggravated renal function in the uninephrectomized ApoE KO mice by increasing kidney lipid accumulation." (PMID 33050202, 2020). "ApoE-knockout [ApoE (-/-)] mice develop chronic inflammation in response to diet-induced hypercholesterolemia and AS features." (PMID 32966239, 2020). "Hypercholesterolemia in apolipoprotein E (ApoE)-/- mice, aggravated by high-fat diet (HFD), produced neutrophilia associated with enhanced lesion size." (PMID 32645995, 2020). "CAV1 and ApoE double-knockout mice are strongly protected against atherosclerotic lesions compared to ApoE-/- mice, despite elevated hypercholesterolemia and hypertriglycemia." (PMID 32082483, 2020). "Eight- to ten-week-old ApoE knock out (ApoE-/-) mice were used to induce hypercholesterolemia with an atherogenic high-cholesterol diet (D12336; Research Diets, Inc., New Brunswick, NJ, USA) for 12 weeks." (PMID 32977607, 2020). "Even if this level is much higher than in patients, the fact that hypercholesterolemia and lesions develop spontaneously on a normal chow diet makes ApoE−/− mice favourable to diet-induced models." (PMID 33258000, 2020). "In the present study, we used ApoE KO mice with unilateral nephrectomy as a model to evaluate the effects of hypercholesterolemia on CKD progression." (PMID 33050202, 2020). "A major mechanism for hypercholesterolemia with APOE4 is through the sequestration of apoE proteins on the hepatic cell surface." (PMID 32587511, 2020).